TMEM150B (transmembrane protein 150B)
Description:
Modulator of macroautophagy that causes accumulation of autophagosomes under basal conditions and enhances autophagic flux. Represses cell death and promotes long-term clonogenic survival of cells grown in the absence of glucose in a macroautophagy-independent manner. May have some role in extracellular matrix engulfment or growth factor receptor recycling, both of which can modulate cell survival.
Synonyms: TMEM224; TTN2; DRAM3
Tractability: Antibody: UniProt places it where antibodies can reach, with high confidence; its Gene Ontology location is reachable by antibodies, with high confidence; UniProt predicts a signal peptide or a membrane-spanning region.
Gene: Protein-coding gene on chromosome 19 (55,312,801 to 55,334,048, reverse strand). Ensembl gene ENSG00000180061.
Subcellular location: Cell membrane; Endosome membrane; Cytoplasmic vesicle, autophagosome membrane
Gene Ontology:
Cellular component: endosome membrane; plasma membrane; autophagosome membrane
Genetic constraint (gnomAD): Loss-of-function variants: 34 observed, 25.53 expected, observed/expected ratio (o/e) 1.33, 90% interval 1.01 to 1.75. The upper end of that interval is the gene's LOEUF score, 1.75, which puts it in group 6 of 6, group 1 being the genes least tolerant of losing a copy. Missense variants: 314 observed, 299.55 expected, observed/expected ratio (o/e) 1.05, 90% interval 0.95 to 1.15. Synonymous variants: 131 observed, 129.96 expected, observed/expected ratio (o/e) 1.01, 90% interval 0.87 to 1.16.
Homologues: Orthologues: chimpanzee TMEM150B (99% identical), macaque TMEM150B (96% identical), dog TMEM150B (77% identical), rabbit TMEM150B (74% identical), guinea pig TMEM150B (73% identical), pig TMEM150B (72% identical), mouse Tmem150b (71% identical), rat Tmem150b (70% identical), tropical clawed frog tmem150b (48% identical), zebrafish tmem150b (41% identical), Caenorhabditis elegans F11E6.6 (18% identical). Paralogues in human: TMEM150A (34% identical), DRAM1 (27% identical), DRAM2 (27% identical), TMEM150C (27% identical).
Diseases named in the same sentence as TMEM150B in open-access papers:
TMEM150B is named in the same sentence as 3 diseases in open-access papers, as found by Europe PMC text mining. Sharing a sentence is not in itself a finding about the gene and the disease. The quoted sentences say what the papers report.
tumor (2 papers, 2020 to 2025). "In addition, using the TIMER algorithm, we found that expression of TMEM150B, SIGLEC1, and CTSW correlated positively with the tumor infiltration levels of B cells, CD8+ T cells, CD4+ T cells, macrophages, and dendritic cells." (PMID 32074080, 2020).
TMEM150B also shares sentences with these, for which no sentence is quoted: cancer (1 paper); endometrial cancer (1).